MIR6739 (microRNA 6739)
Synonyms: hsa-mir-6739
Gene: MicroRNA gene on chromosome 1 (201,863,373 to 201,863,447, forward strand). Ensembl gene ENSG00000277681.
Homologues: Orthologues: chimpanzee MIR6739 (100% identical).